ERICH5 (glutamate rich 5)
Synonyms: C8orf47; FLJ39553
Tractability: PROTAC: ubiquitination databases record sites on it.
Gene: Protein-coding gene on chromosome 8 (98,064,271 to 98,095,512, forward strand). Ensembl gene ENSG00000177459.
Subcellular location (Human Protein Atlas): Golgi apparatus; Cytosol; Nucleoplasm
Pathways (Reactome):
Developmental Biology: Developmental Lineage of Pancreatic Ductal Cells
Gene Ontology:
Molecular function: protein binding
Genetic constraint (gnomAD): Loss-of-function variants: 23 observed, 28.4 expected, observed/expected ratio (o/e) 0.81, 90% interval 0.58 to 1.15. The upper end of that interval is the gene's LOEUF score, 1.15, which puts it in group 5 of 6, group 1 being the genes least tolerant of losing a copy. Missense variants: 405 observed, 437.03 expected, observed/expected ratio (o/e) 0.93, 90% interval 0.85 to 1.01. Synonymous variants: 156 observed, 156.8 expected, observed/expected ratio (o/e) 0.99, 90% interval 0.87 to 1.14.
Homologues: Orthologues: chimpanzee ERICH5 (99% identical), mouse Erich5 (50% identical), rat Erich5 (45% identical).
Diseases named in the same sentence as ERICH5 in open-access papers:
ERICH5 is named in the same sentence as 2 diseases in open-access papers, as found by Europe PMC text mining. Sharing a sentence is not in itself a finding about the gene and the disease.
ERICH5 shares sentences with these, for which no sentence is quoted: cancer (2 papers); tumor (2).